ARG2 (arginase 2)
Diseases named in the same sentence as ARG2 in open-access papers (continued):
Sharing a sentence is not in itself a finding about the gene and the disease.
asthma (15 papers, 2012 to 2024). "In their asthma cohort, ARG2 variants associated with lower arginase activity, combined with high levels of fractional exhaled nitric oxide identified a more severe asthma phenotype." (PMID 36441389, 2023). "Asthmatics with high FeNO had higher expression of iNOS and ARG2 in the airway, which was associated with more severe asthma." (PMID 38203630, 2023). "ARG2 gene variants are among the first and most consistently found single nucleotide polymorphisms (SNPs) associated with asthma in genome-wide association studies (GWAS)." (PMID 36441389, 2023). "The study of the ARG2 polymorphism rs7140310 did notidentify statistically significant differences in the allele andgenotype frequency distributions between asthma patientsand controls of different ethnicity ( p > 0.05)." (PMID 33659822, 2020). "Theassociation analysis of the ARG2 polymorphism rs3742879with asthma in individuals of different ethnic origin did notreveal statistically significant differences between groups ofpatients and controls ( p > 0.05)." (PMID 33659822, 2020). "Allele and genotype frequencies of four polymorphisms of arginaseARG1 (rs2781667) and ARG2 (rs17249437, rs3742879,rs7140310) genes were analyzed in asthma patients and healthyindividuals from the Republic of Bashkortostan." (PMID 33659822, 2020). "Vonk J.M., Postma D.S., Maarsingh H., Bruinenberg M., KoppelmanG.H., Meurs H. Arginase 1 and arginase 2 variations associatewith asthma, asthma severity and β2 agonist and steroidresponse." (PMID 33659822, 2020). "The arginase 2 genes variations associate with steroid response, which probably plays an important role in asthma development, severity and progression." (PMID 28769946, 2017). "Thus, an association study of polymorphic variants of ARG1and ARG2 genes involved in beta-2-agonists metabolismwas carried out in asthma patients and corresponding controlgroups from the Republic of Bashkortostan." (PMID 33659822, 2020). "The arginine metabolism seems to be a critical modulator of severity of inflammation and remodeling in both eosinophilic and neutrophilic asthma, while arginine metabolism via ARG2 suppresses inflammation and, via iNOS, promotes airway inflammation." (PMID 38203630, 2023). "The upregulatory effect of ASA on ARG2 mRNA levels points to a novel mechanism for AR in aspirin-intolerant asthma." (PMID 36061615, 2022). "It has been shown that both ARG1 and ARG2 are expressed in the airways and are upregulated in animal models of asthma as well as in patients." (PMID 36061615, 2022). "In this paper, we analyzedassociations of arginase ARG1 (rs2781667) and ARG2(rs17249437, rs3742879, rs7140310) gene polymorphismswith asthma development and course and with sensitivity totherapy in patients." (PMID 33659822, 2020). "Arginase genetic polymorphisms (rs2781667 of the ARG1 gene, rs17249437, rs3742879,rs7140310 of the ARG2 gene) were studied in 236 children with asthma and 194 unrelated healthy individualsof Russian, Tatar and Bashkir ethnicity from the Republic of Bashkortostan." (PMID 33659822, 2020). "Beta-2-agonists are some of the major class of bronchodilators used for asthma management.According to published data, allelic variants of the arginase ARG1 and ARG2 genes are associated with a risk ofasthma development, spirometry measures and efficacy of bronchodilator therapy." (PMID 33659822, 2020). "However, the associations of FeNO with DNA methylation of other asthma gene promoters (i.e., IFNγ and ARG2) were not significant in adjusted models (p > 0.05)." (PMID 28588744, 2017). "Arginine metabolism is important in type 2 high airway inflammation and asthma, generating NO by several enzymes, including inducible nitric oxide synthase (iNOS), arginase-1 (ARG1), and ARG2." (PMID 38555460, 2024). "In the mouse model of asthma consisting of NOS2 knockout mice, allergen challenge upregulated protein levels of ARG1 and ARG2 40-fold and 4-fold, respectively." (PMID 36061615, 2022).
asthma (continued). "CpG promoter loci of asthma genes (i.e., interleukin 4 (IL4), interferon gamma (IFNγ), inducible nitric oxide synthase (NOS2A), arginase 2 (ARG2)) were pyrosequenced and lung function was assessed." (PMID 28424066, 2017). "Severe asthmatics had the highest FENO levels (ANOVA P = 0.003), but similar expression of iNOS and ARG2 proteins in the airway epithelium (both ANOVA P > 0.05) as compared to individuals with mild and moderate asthma." (PMID 28797075, 2017). "Retnla, Saa3, Scin, Arg2, and Fcgbp were increased in OVA-challenged mice relative to control mice, may be useful as biomarkers of asthma." (PMID 29086354, 2018). "Though higher values of ARG2 were likewise found in the subgroups of patients with CRS and no asthma, the results were not statistically significant." (PMID 31683763, 2019). "Similar associations were not apparent between BC and DNA methylation of other asthma gene promoters (i.e., IFNγ, NOS2A, and ARG2) in unadjusted and adjusted models (p > 0.05)." (PMID 28588744, 2017).
diabetes (14 papers, 2013 to 2026). "In conclusion, insulin therapy restored the diabetes-induced loss of renal NEP protein and decreased the diabetes-induced rise in renal Arg-2 protein, suggesting a reversal of critical molecular changes in the diabetic kidney." (PMID 41601953, 2026). "Diabetes and high glucose models in vitro and in rodents have been associated with increased arginase activity and increased expression of both arginase isoforms, arginase-1 and arginase-2." (PMID 40076703, 2025). "Because ARG2 levels increase in diabetic patients and are mitigated by insulin treatment, patients with history of diabetes were excluded from the study." (PMID 28808255, 2017). "Indeed, polymorphisms in ARG1, ARG2, DDAH 1, DDAH 2, AGXT2 and VEGF were associated to altered risk forcardiovascular diseases, diabetes mellitus and preeclampsia." (PMID 36264109, 2022). "Hepatocyte-specific Arg2 overexpression increases basal thermogenesis, enhances insulin sensitivity, and decreases hepatic steatosis and inflammation in genetic and diet-induced models of diabetes and NAFLD." (PMID 30962478, 2019). "Third, post-treatment of HXSF ameliorated the diabetes-elevated ROS, inflammatory cytokines and glomerular hyper-filtration, companied with lower levels of arginase activity, arginase 2 and heparanase expression and levels of HS expression in glomerular region." (PMID 30319431, 2018). "While veryinteresting, to date no clinical study assessed whether ARG1and ARG2 SNPs would associate with diabetes end-organ damage,which is decurrent mostly by low oxygenation and oxidative stress induced byhypercontractility of peripheral vessels." (PMID 36264109, 2022). "Arginase-2 is located in the mitochondria and has been found to promote neurovascular degeneration in I/R and OIR mouse models and to increase expression of inflammatory mediators and promote cell death in murine and in vitro diabetes models." (PMID 40076703, 2025). "In the current study, we used ABH that inhibits both isoforms, so this does not rule out the potential involvement of arginase 2 in inducing retinal endothelial cell senescence in diabetes." (PMID 29673160, 2018).
pancreatic cancer (14 papers, 2013 to 2025). "Arginase 2 is reported to be synthesized by cancer-associated fibroblasts (CAFs) in pancreatic cancer, and our data would thus suggest a possible role for CAF-derived arginase 2 in the immunosuppressive environment of low immune/β-catenin high CIC4." (PMID 29664013, 2018). "ARG2 was also found to play a critical role in obesity-associated pancreatic cancer (PDA)." (PMID 36010962, 2022). "So far, direct evidence for CAFs inducing T cell suppression via arginase has not been provided, although clinical data clearly show that ARG2 overexpression by CAFs predisposes to poor overall survival in pancreatic cancer and ARG2 production by CAF has been observed in unrelated solid tumors, too." (PMID 32328671, 2021). "Upregulated Arg2 has been reported in a variety of cancers, including melanoma and pancreatic cancer, and the suppression of arginase inhibits tumor cell growth and metastasis." (PMID 36604146, 2022). "Research addressing the expression of arginase II (ARG2) in pancreatic cancer and its role in immune suppression revealed that the majority of ARG2 is present in cancer-associated fibroblasts (CAFs) in hypoxic state." (PMID 32707920, 2020). "To investigate the role of ARG2 in the metabolism of pancreatic tumors, we performed unbiased global metabolite profiling and found that nitrogen-centric pathways enriched in urea cycle metabolites were highly impacted by ARG2 knockdown." (PMID 28808255, 2017). "OATD-02 may demonstrate effectiveness in the treatment of immune-related cancers and in cancers with enhanced ARG2 expression, such as pancreatic cancer, chronic and acute myeloid leukemia, kidney cancer, and in patients with prostate cancer." (PMID 39337272, 2024). "Our findings point to an essential in vivo role for ARG2 in pancreatic cancer, an insidious malignancy with enhanced protein breakdown and remodeling, and suggest a potential need for the channeling of nitrogen into the urea cycle in highly proliferative tumors." (PMID 28808255, 2017). "The direct effect of ARG2 induced by exposure to hypoxia in CAFs against cancer cells was investigated using an in vitro system in which CAFs extracted from PDC tissues were co-cultured with pancreatic cancer MiaPaCa-2 cells." (PMID 23424623, 2013). "In pancreatic cancer samples tested by the International Cancer Genome Consortium, only 1% contained ARG1 mutations, and no ARG2 mutations were seen." (PMID 28098776, 2017).
melanoma (12 papers, 2018 to 2025). A malignant, usually aggressive tumor composed of atypical, neoplastic melanocytes. "In melanoma, the overexpression of ARG2 in Treg increases their accumulation in tissues and suppressive capacity for the inhibition of mTOR signaling by the modulation of the PI3K/AKT/mTOR signaling pathway." (PMID 39337272, 2024). "The adoptive transfer of CD8+ T cells with Arg2 knockout reduced tumor growth in murine model of melanoma and colon cancer." (PMID 39337272, 2024). "Mice bearing either B16 (BRAFWTPTENWT) or BPR20 (BRAFV600EPTEN-/-) melanomas were treated with STING agonist ADU-S100 plus various inhibitors of ARG2, COX2, NOS2, PD-L1, or ISG15." (PMID 38312842, 2024). "Compared to the control group,Arg2 knockout or arginase inhibition with BEC further decreased the melanoma tumor size of sorafenib-treated mice." (PMID 36604146, 2022). "In this study, we show that sorafenib treatment leads to melanoma cell death and a decrease in Arg2 at both the mRNA and protein levels." (PMID 36604146, 2022). "Our data agree with other studies showing the prognostic potential of ARG2,22,43, 44, 45 while a recent study showed that ARG2 promotes melanoma progression and metastasis through STAT3 signalling, also involved in BM." (PMID 36423363, 2022). "Clinical database analysis for melanoma shows that Arg2 is remarkably upregulated in melanoma patients compared to the normal group." (PMID 36604146, 2022). "Our previous studies demonstrated that Arg2 is able to promote melanoma cell proliferation through polyamine and metastasis-related processes independent of its enzymatic activity." (PMID 36604146, 2022). "Emerging evidence has demonstrated that arginase 2 (Arg2), type 2 of arginase, is elevated in various types of cancers including melanoma." (PMID 36604146, 2022). "Transcriptomic analyses of Tregs isolated from human melanomas demonstrated an increased expression of mitochondrial arginase 2 (ARG2) enzyme and enhanced Treg suppressive capacity." (PMID 33532902, 2021). "While therapeutic STING agonism coordinately enhanced expression of the Arg2, Isg15, Nos2, and Pdl1 (Cd274) immuno-suppressive/regulatory ISGs in both melanoma models, Cox2/Ptgs2 expression was selectively upregulated by ADU-S100 treatment only in the B16 model." (PMID 38312842, 2024). "Moreover, ARG2 can promote cancer metastasis through the mitochondrial H2O2-STAT3 pathway in melanoma." (PMID 39337272, 2024). "Sorafenib induces melanoma cell death through decreasing expression of Arg2." (PMID 37795022, 2023). "Whether the Arg2-Akt-GPX4 axis modulates sorafenib-induced ferroptosis in human melanoma cells requires further validation." (PMID 36604146, 2022). "Moreover, genetic depletion of Arg2 expression and pharmacological suppression of Arg2 activityin vitro andin vivo ameliorate the antitumour activity of sorafenib in melanoma cells." (PMID 36604146, 2022). "Moreover, Genotype-Tissue Expression (GTEx) and Cancer Genome Atlas (TCGA) database analyses revealed that Arg2 mRNA expression level was abnormally upregulated in melanoma patients compared to that in the normal group." (PMID 36604146, 2022). "In our study, it is important to note that sorafenib-induced ferroptosis, GPX4 decrease and lipid peroxidation were accompanied by downregulation of Arg2 expression and Akt phosphorylation in mouse melanoma cells, which can be prevented by overexpression of Arg2." (PMID 36604146, 2022). "In our previous study, immunofluorescence staining analysis of clinical human melanoma specimens confirmed that Arg2 expression was remarkably upregulated in melanoma patients, suggesting that Arg2 plays a potential role in promoting melanoma cell growth or antagonizing melanoma cell death." (PMID 36604146, 2022). "Arginase 2 (Arg2) promoted GPX4 expression and inhibited lipid peroxidation, whereas sorafenib downregulated Arg2 expression to induce ferroptosis in melanoma." (PMID 40497999, 2025).
melanoma (continued). "In the present study, we demonstrate that sorafenib treatment leads to the downregulation of Arg2 at the mRNA and protein expression levels, which suppresses ferroptosis by activating the Akt/GPX4 signaling pathway in mouse melanoma cells." (PMID 36604146, 2022). "We also show that Arg2 suppresses ferroptosis by activating the Akt/GPX4 signaling pathway, negatively regulating sorafenib-induced cell death in melanoma cells." (PMID 36604146, 2022). "Interestingly, with the occurrence of ferroptosis, Arg2 was specifically downregulated in melanoma cells in response to sorafenib and erastin, indicating that Arg2 may promote melanoma cell growth or inhibit ferroptosis, which is in agreement with our previous study." (PMID 36604146, 2022). "In addition, Arg1 was barely detected in B16F10 and ME276 cells with or without sorafenib, suggesting that Arg2 is the single isoform expressed in murine melanoma." (PMID 36604146, 2022). "Regarding the role of MYO1B in cell apoptosis, it promotes apoptosis in senescent cells through ARG2-induced over-activation of MTORC1-RPS6K1 signaling, whereas it antagonizes apoptosis by preventing nuclear accumulation of PTEN in immortalized cells and tumor cells such as melanoma." (PMID 31349190, 2019). "In the B16 melanoma model, we noted improved antitumor efficacy only when ADU-S100 was combined with neutralizing/blocking antibodies against PD-L1 or ISG15, but not inhibitors of ARG2, COX2, or NOS2." (PMID 38312842, 2024).
breast carcinoma (11 papers, 2013 to 2025). "Knocking down ARG2 in breast cancer cells significantly inhibits cell proliferation and causes G2/M arrest, without compensation through the OAT pathway." (PMID 39973065, 2025). "In previous studies, high ARG2 expression was linked to worse metastasis-free and overall survival in patients with primary breast cancer." (PMID 40140975, 2025). "Breast cancer cells rely on ARG2 for ornithine synthesis, while normal cells use ornithine aminotransferase (OAT)." (PMID 39973065, 2025). "This is consistent with a strong enrichment of ARG2 expression in the Luminal subgroup of breast cancer cell lines, and some enrichment in Basal A, compared to Basal B." (PMID 31430931, 2019). "Transcriptomic analyses of neutrophils from the spleen and blood of breast cancer-bearing mice revealed that tumour-induced neutrophils produce ROS, NO, and arginase 2(ARG2), suppressing T-cell proliferation ex vivo and demonstrating an immunosuppressive N2-like phenotype." (PMID 41451221, 2025). "Meanwhile, Arginase-1 (ARG1) and arginase-2 (ARG2), which converted arginine to ornithine and urea, were highly expressed in various tumors such as breast cancer and neuroblastoma, as well as cancer-associated cells such as fibroblasts and myeloid-derived suppressor cells (MDSCs)." (PMID 36798123, 2023). "ARG2 expression was increased in prostate cancer, breast cancer and glioblastoma." (PMID 36817446, 2023). "While TXNDC12 has not been studied in breast cancer, two gene family members of TXNDC12, ARG2 and ARG3, are known serum-based breast cancer biomarkers." (PMID 37128318, 2023). "Whilst ARG1 was not expressed, ARG2 mRNA was found in all breast cancer cell lines." (PMID 40140975, 2025).
Hypertension (11 papers, 2012 to 2026). The presence of chronic increased pressure in the systemic arterial system. "A recent study reported that ARG2 upregulation activated by hypoxia contributes to a lower NO availability in hypoxia-induced hypertension." (PMID 36209203, 2022). "Hypertension also has been reported in 24 wk old Akita mice accompanied with renal hypertrophy and dysfunction, but was not present in 16 wk old Akita mice, which also displayed renal dysfunction and elevated kidney Arg2 activity and expression." (PMID 23977269, 2013). "A progressive hypertension has been reported for ARG2 KO mice." (PMID 23908657, 2013). "However, whether ARG1 and ARG2 differ in the development of hypertension warrants further investigation." (PMID 36209203, 2022). "Hypertension was induced in wild type (WT), partial ARG1+/− knockout (KO), and complete ARG2−/− KO mice by uninephrectomy and deoxycorticosterone acetate (DOCA)-salt treatment for 6-weeks." (PMID 23908657, 2013).
neuroblastoma (8 papers, 2017 to 2023). Neuroblastoma (NB) is the most common solid, extracranial childhood tumor. "Arginase 2 (ARG2) drives neuroblastoma cell proliferation via regulation of arginine metabolism, which polarizes infiltrating monocytes to an M1 macrophage phenotype, releasing IL-1β and TNF-α in an RAC-α serine/threonine protein kinase (AKT)-dependent manner." (PMID 37491279, 2023). "In neuroblastoma, tumor cell ARG2 activity leads to both suppression of autologous and engineered anti-tumor immunity." (PMID 30728077, 2019). "ARG2 was shown to be important in T cell suppression in leukemia and neuroblastoma." (PMID 30728077, 2019).